IL18 (interleukin 18)
Diseases named in the same sentence as IL18 in open-access papers (continued):
Sharing a sentence is not in itself a finding about the gene and the disease.
infection (continued). "A study in Myd88-/- mice infected with L. major has highlighted the importance of TLRs, IL-1 and/or IL-18 in the induction of IL-12 and the generation of Th1 responses; MyD88 deficiency also resulted in complete abrogation of IFNγ production by CD4+ T cells and an inability to control infection." (PMID 21253574, 2011). "Infection activates the NLRP3 inflammasome via ROS, cathepsin B, and potassium efflux, promoting IL-1β/IL-18 secretion and ASC oligomerization." (PMID 42245999, 2026). "Levamisole significantly inhibited IL-1β, IL-6, IL-8, IL-18, TNF-α, and COX-2 mRNA expressions in the spleen compared to the infection group (p < 0.001)." (PMID 40427533, 2025). "In further experiments, we assessed the influence of IL-18 on the de novo induction of CD8+ T cells, which is potentially more relevant than recall responses in the context of primary infection with SARS-CoV-2." (PMID 39847442, 2025). "The data indicated that IL-1β, IL-6, IL-8, IL-18, TNF-α, and COX-2 mRNA levels in the spleen in the infection group were significantly upregulated (p < 0.001)." (PMID 40427533, 2025). "The IL-1β, IL-18, and TNF-α protein levels were increased in the infection group compared with the control group (p < 0.001)." (PMID 40305201, 2025). "There were also differences in the slopes of the simple linear regression lines between other proteins (IL-18, C3, IL-10, and CD163) and time post infection that further highlighted the dissimilarity between Cov and nLongC immune recovery (Figure A1)." (PMID 41369364, 2025). "Pro-inflammatory cytokines are released by infection, including TNF-α, IL-6, and IL-18, mediating inflammation and clinical symptoms." (PMID 40034419, 2025). "The IL-1β, IL-18, and TNF-α mRNA levels were decreased in the Pro10, Pro20, Pro40, Amo20, Pro20 + Amo20, and Bai100 groups compared with the infection group (p < 0.001)." (PMID 40305201, 2025). "IL-1β, IL-18, and LDH levels in the BALF 5 days after MPXV infection exhibited an AIM2-dependent effect." (PMID 41225161, 2025). "However, since all three cytokines play an important role in host defense against infection as well as in the pathogenesis of autoimmune and inflammatory diseases, a therapy that concomitantly targets the release of IL-1α, IL-1β and IL-18 is of high clinical interest." (PMID 41221292, 2025). "This inflammasome triggers the release of IL-18 and GSDMD-dependent pyroptosis in intestinal epithelial cells and restricts infection by the dsRNA virus rotavirus." (PMID 41062723, 2025). "The IL-1β, IL-18, and TNF-α protein levels were reduced in the Pro10, Pro20, Pro40, Amo20, Pro20 + Amo20, and Bai100 groups compared with the infection group (p < 0.05) (except TNF-α in the Pro10 group)." (PMID 40305201, 2025). "On the other hand, pro-inflammatory cytokines IL-1β, IL-7, IL-18, and chemokines MCP-1 and MIP-1α were upregulated after infection with rCDC-9 P11 compared to rCDC-9 P45." (PMID 41060027, 2025). "Our findings indicated that MPXV infection promoted CASP1-dependent cleavage of CASP1 and the release of the inflammasome-driven cytokines IL-1β and IL-18, suggesting that MPXV is involved in inflammasome activation." (PMID 41225161, 2025). "This preceded the transcriptional upregulation of inflammatory cytokines, including IL-1β, IL-6, IL-18, and TNF-α, which only became prominent at 12-24 hours post-infection." (PMID 41281739, 2025). "We previously found that EBV also upregulates IL-18, TNF-α, and IFN-γ mRNAs within the first week of infection." (PMID 40674368, 2025). "When the piglets were administered levamisole or baicalin, the mRNA expression levels of IL-1β, IL-18, and TNF-α in the blood vessels were weakened compared to the infection group (p < 0.001)." (PMID 40427615, 2025). "In a low-dose infection model, AIM2 inhibition reduced IL-1β and IL-18 production, LDH release, and tissue pathology." (PMID 41225161, 2025).
infection (continued). "In the present research, at 28 days post-infection, CD11d expression was markedly elevated in cardiac tissue, whereas levels of TNF-α, IL-1β, and IL-18 remained within the normal range." (PMID 41472298, 2025). "Cytokine profiling revealed elevated levels of TNF, IL-8, IL-10, and reduced levels of IL-18 and CCL2 in culture supernatants over the time of infection." (PMID 40794782, 2025). "For example, at 11 DoA (4 days post infection), TLR4 and CSF2RA expressions were correlated to Enterococcus and IL18 (a pro-inflammatory cytokine known for its ability to enhance the production of interferon-gamma) to Salmonella." (PMID 40079593, 2025). "As for IL-18, in L. major–infected BALB/c mice, this cytokine was shown to upregulate IL-4 production, favoring the persistence of infection." (PMID 38707903, 2024). "We provide in vivo evidence that caspase-1 expression is critical for, IL-18 release, optimal interferon-γ (IFN-γ) production, monocyte and neutrophil recruitment to the site of infection, and parasite control." (PMID 39446964, 2024). "At day eight post-infection, we performed ELISAs on the serum and found that Cx3cr1+Casp1 KO mice had decreased IFN-γ levels, comparable IL-12 levels, and decreased IL-18 levels compared to WT mice." (PMID 39446964, 2024). "Forty-eight hours after G. parasuis challenge, IL-1β, IL-10, IL-18, TNF-α and IFN-γ mRNA expression was increased, and IL-2 and IL-8 mRNA expression was decreased in the infection group compared to the control group (P < 0.001)." (PMID 39075562, 2024). "We wanted to assess the suitability of the levels of biomarkers tested: interleukin (IL)-17A, IL-18, IL-23, normal T cells expressed and secreted (RANTES), and induced protein (IP)-10, as well as immunoglobilun G4 (IgG4) to predict recurrent infections." (PMID 39431236, 2024). "In conclusion, we showed that in a mouse model of Pm infection, GA significantly reduced Pm-induced vascular inflammatory injury, and decreased PARP1, HMGB1, IL-1β, and IL-18 protein expression in vascular tissue." (PMID 39850582, 2024). "At different time points post infection, we monitored the mRNA level for the cytokines TNF-α, IL-8, IL-12 and IL-18 by qRT-PCR." (PMID 39104852, 2024). "IL-12 and IL-18 transcripts were maintained relatively low level in PEDV CV777-infected cells; in contrast, infection of IPEC-J2 with PEDV for 48 h and 72 h induced a sharp increase of TNF-α and IL-8 transcripts." (PMID 39104852, 2024). "IL-10 was significantly increased in CC061 mice after MRSA infection, while IL-1β, IL-4, IL-9, IL-18, IL-23, and IL-27 were significantly increased in CC024 mice after infection." (PMID 39178306, 2024). "The hyporesponsiveness to IL-12 and IL-18 stimulation for both cytotoxicity responses and IFN-γ production observed in the Ascaris-single infection and coinfection implies that Ascaris clearly impedes the functionality of NK cells." (PMID 38918457, 2024). "After the piglets were challenged with G. parasuis for 48 h, the IL-1β, IL-10, IL-18, TNF-α and IFN-γ mRNA expression levels in the blood of the infection group were significantly greater than those in the blood of the control group (p < 0.01)." (PMID 39075542, 2024). "Compared with infection alone, levamisole and BMS-1 reduced IL-1β, IL-10, IL-18, TNF-α and IFN-γ mRNA expression and increased IL-2 and IL-8 mRNA expression (P < 0.01)." (PMID 39075562, 2024). "IL-1β and IL-18, elevated in CC024 mice after infection, act on lymphoid cells and enhance the production of IL-22." (PMID 39178306, 2024). "Then, we monitored the amount of pro-inflammatory cytokines interleukin-1β (IL-1β), IL-18 and tumor necrosis factor-α (TNF-α) during infection." (PMID 39376663, 2024). "To investigate the role of M84 in regulating IL-18 levels in vivo, we measured IL-18 levels in the serum of MCMV-infected mice at 1.5 and 3 days post-infection." (PMID 38278864, 2024).
infection (continued). "In the early stages of IAV infection (the first five days after infection), the activation of NLRP3 triggers the release of inflammatory factors such as IL-1 β and IL-18, which help recruit immune cells and improve their ability to fight the virus." (PMID 38399989, 2024). "Cytokines with post-hoc statistical power > 0.7 are sCD30, SDF-1α, IFN-γ, SCYB16, M-CSF, I-309, TNF-α, IL-8, IL-18, and sTNF-R2 in SARS-CoV-2 infection vs. non-infection." (PMID 38476443, 2024). "IL-18 collaborates with IL-12 to stimulate NK cells to produce IL-8, IFN-γ and TNF-α, enhancing their activities against infection and cancer whilst triggering an innate immune response." (PMID 39554494, 2024). "This adaptive immunity includes promoting Th1 responses to produce proinflammatory cytokines, such as IL-1β, IL-18, IL-12, tumor necrosis factor (TNF-α), and interferon (IFN)-γ to effectively clear the infection." (PMID 38623843, 2024). "At 4h post-infection, LV-NLRP12 cells showed elevated CASP1 and GSDMD cleavage, followed by higher levels of active IL−1β and IL-18." (PMID 39119293, 2024). "Multiple waves of type I IFN production, starting with IFN-β at 12 h post-infection, are responsible for the induction of inflammatory monocyte recruitment, leading to IFN-γ production in NK cells induced by interleukin 18 (IL-18)." (PMID 39598474, 2024). "Based on the results, the mRNA levels as well as IL-1β, IL-6, IL-8, IL-10, IL-18, TNF-α and IFN-γ were significantly upregulated, and the IL-2 level was decreased in the infection group compared to the control group (p < 0.05)." (PMID 38582846, 2024). "The results demonstrated that untreated A549 cells infected with B. pseudomallei expressed significantly higher amounts of MIF, PAI-1, IL-18, CXCL1, CXCL12 and IL-8 when compared with uninfected cells at 12 h post-infection." (PMID 36758060, 2023). "The early wave of IFN-β (12 h after infection) led to the induction of MCP-1-mediated inflammatory monocyte recruitment, subsequently leading to IL-18-induced NK cell IFN-γ production." (PMID 37765155, 2023). "When infection and cellular injury occur, the NLRP3 inflammasome can activate caspase-1 and then induce the activation of the inflammatory cytokines IL-1β and IL-18." (PMID 36713830, 2023). "After 48 h of infection, LMH cells infected with FAdV-4 GY (group A) showed significant upregulation of the transcription levels of most immuno-cytokines (IL18, TLR7, IFN-α, and IFN-β excepted), such as OASL, Mx, MDA5, and MAVS." (PMID 37896849, 2023). "In particular, we found increased TGF-β1, FGF23, NGAL, IL-18, HIF1-α, TLR2, YKL-40, and B2M mRNA levels long-term post MHV-1 infection." (PMID 37626956, 2023). "Our results show that the infection of mice with SARS-CoV-2 induces the expression of several pro-inflammatory CC and CXC chemokines activated through NF-κB but weakly IL1β and IL18 whose expression are more characteristic of inflammasome formation." (PMID 36851549, 2023). "To determine if PAM-Tang cells exposed to S. suis have the ability to secrete pro-inflammatory cytokines, we used ELISA kits to detect the pro-inflammatory cytokines IL-18, IL-1β, and TNF-α secreted by PAM-Tang cells at different times post-infection." (PMID 36677452, 2023). "The HLA-A11/DR1 mice strain induced lower levels of several cytokines (IL-2, IL-10, IL-18, IL-1β, TNF-α, IL-1α, IL-28, and ENA78), but showed increased secretion of IFN-γ, RANTES, IP10, and Eotaxin at 12 h post-infection, compared to the WT group." (PMID 38035330, 2023). "Regarding the mRNA expression, a significant increase in TGF-β1, HIF-1α, NGAL, B2M, FGF23, TLR-2, IL-18, and YKL-40 was observed in the long-term post-MHV-1 infection, whereas only NGAL was found to be significantly increased in the acute stage post-infection." (PMID 37626956, 2023).
infection (continued). "In response to infection mediated by CD16 and ACE2 receptors, human macrophages activate inflammasomes, release IL-1 and IL-18 and undergo pyroptosis, which leads to the hyperinflammatory state of the lungs." (PMID 37113134, 2023). "Cell death and IL-18 release were significantly reduced in unprimed and IFN-γ-primed hMDMs treated with CASP4 or both CASP4 and CASP5 siRNA prior to infection with T4SS+ Lp, compared to control siRNA-treated cells." (PMID 37737612, 2023). "IL-18 and IFN-γ are critical in human immunity and broadly protective against infection, therefore, they are commonly studied using primary human cells such as whole blood or PBMCs." (PMID 37068092, 2023). "The mRNA expression levels of IL-6, IL-18, IFN-α, IFN-β, and ISG-15 were up-regulated during EV-G/YN23/2022 infection, while IL-1β, TNF-α, IFN-λ3, and IRF-7 maintained in relatively constant levels, and no cytokines were significantly reduced." (PMID 37632087, 2023). "The pro-inflammatory cytokines (Th1 immune response) (IL-1, IL-2, IL-6, IL-8, IL-18, IFN-γ, and TNF-α) generally regulate growth, cell activation, differentiation, and homing of the immune cells to the infection sites." (PMID 38133693, 2023). "Infection with these bacteria induced solid inflammatory responses and a substantial increase in the inflammatory cytokine release of TNF‐α, IL‐6, IL‐1β, and IL‐18 in macrophages derived from March5fl/fl mice." (PMID 37575012, 2023). "After the adjustment of operating time and intraoperative hypotension, levels of IL-6 (Prep, POD1, POD2), IL-12 (POD1, POD2), IL-18 (POD1, POD2), and IL-8 (POD2) were found to be correlated with postoperative infection outcomes (p < 0.05)." (PMID 36299462, 2022). "Infection with subAB-positive STEC O113:H21 (wild-type STEC O113:H21 [STEC O113 WT]) resulted in release of IL-1β and IL-18 from murine macrophage cell line J774.1 cells." (PMID 35345462, 2022). "Immunization of animals with the recombinant LSDV Atyrau-5BJN(IL18) at a dose of 6000 TCID50 induced the production of virus-neutralizing antibodies and protected the animals from infection with the virulent LSDV." (PMID 36298570, 2022). "Transcripts encoding cytokines and chemokines such as IL-1β (interleukin-1β), IL-18, IL-6, IFN-γ, IL-10, CCL2 (C-C motif chemokine ligand 2), CCL4 and CCL7 were also up-regulated in the lungs during infection." (PMID 34965194, 2022). "During the early phase of infection (days 1–3 post-infection (p.i.)), the transcription of proinflammatory factors (i.e., IL-12, IFN-γ, TNF-α, IL-1β, IL-6, IL-18) was induced faster under BaP exposure." (PMID 35203386, 2022). "In response to infection mediated by CD16 and ACE2 receptors, human macrophages activate inflammasomes, release IL-1 and IL-18 and undergo pyroptosis thereby contributing to the hyperinflammatory state of the lungs." (PMID 35483404, 2022). "Following overnight stimulation with IL-12 plus IL-18, IFN-γ production by maternal NK cells was strongly increased in healthy donors and recovered patients, but much less in mothers with ongoing infection, and more especially in symptomatic patients." (PMID 35911747, 2022). "For example, to establish an infection, DENV requires T helper 1 (TH1) responses which stimulate the production of interleukin-12 (IL-12), interleukin-18 (IL-18), tumor necrosis factor (TNF), and IFN-γ." (PMID 36189361, 2022). "The results of our study demonstrated that IL-1β/IL-18 levels were significantly elevated in the culture supernatants of macrophages infected with E.coli HPI, with higher levels detected following infection with the strain carrying the irp2 gene." (PMID 33678162, 2021). "To determine the contribution of ASC-dependent inflammasomes to IL-1β and IL-18 production in HSE, we assayed mice early after infection and prior to mortality (days 1 and 3)." (PMID 33524073, 2021).
infection (continued). "We found the expressions of mRNA expression of caspase-1, GSDMD, caspase-3, MLKL, RIPK3, NLRP3, IL-1β and IL-18 and of proteins cleaved caspase-1, GSDMD, cleaved caspase-3 and pMIKL in the macrophages of the three infection groups to be upregulated (P<0.05)." (PMID 34513732, 2021). "Of interest, the impact of IL-18 level changes on appetite changes was independent from the CRP level and infections." (PMID 34444668, 2021). "Suggesting low systemic response, the blood of mice trained 9 weeks contained lower levels of a broad range of cytokines (IL-1β, IL-6, IL-10, IL-12p40, IL-17A, IL-18, IFNγ, TNF, CCL2 and CXCL5) 2 days after infection with L. monocytogenes." (PMID 34603295, 2021). "The IL-1β and IL-18 content in the control group was significantly lower than those in the HPI infection groups at 6 and 9 h post-infection (P < 0.01)." (PMID 33678162, 2021). "Recruitment and NK cells’ activation at the site of infection requires chemokines (ligands for CCR2, CCR5, and CXCR3) and cytokines (IL-12 and IL-18) secreted from myeloid cells, mainly monocytes and macrophages." (PMID 34305935, 2021). "The expression of IL-1β, IL-6, IL-8, IL-18, TNF-α, MMP-9, RANKL, TLR-2, TLR-4, TLR-6, thymic stromal lymphopoietin (TSLP), and ICAM-1 was evaluated by qPCR at 2 and 24 h after infection." (PMID 33802988, 2021). "IL‐1β, IL‐6, and TNF‐α are important for acute phase protein production and fever induction, while IL‐12, IL‐18, and IFN‐γ recruit neutrophils to the site of infection and elicit a T helper type 1 (Th1) adaptive immune response." (PMID 33970545, 2021). "The cytokines are complemented by infection and inflammation related proteins such as IL6 or IL18 and TNF, the key players in infectious disease states with both beneficial and harmful, pleiotropic activities." (PMID 35145507, 2021). "The IL-1β and IL-18 expression levels in the HPI+ group were significantly different from those in the control and HPI− groups at 6 and 9 h post-infection (P < 0.01)." (PMID 33678162, 2021). "Infection also led to upregulation of the CCL2 chemokine and the IL-18 pro-inflammatory interleukin." (PMID 33921891, 2021). "At 3 weeks after infection, the levels of IL-1β in BALF and IL-18 in serum from Aim2-/- mice are lower than that from WT mice." (PMID 33503864, 2021). "HPI+/HPI−-infection was accompanied by upregulated expression levels of NLRP3, ASC, caspase-1, IL-1β, IL-18 and GSDMD, with significantly higher levels detected in the HPI+ group compared to those in the HPI− group (P < 0.01 or P < 0.05)." (PMID 33678162, 2021). "Similar to what was observed at 24 hours post-infection, HSV-1 infection of the WT, ΔAIM2, and ΔIFI16 THP-1 cells led to significant IL-18 production." (PMID 32101570, 2020). "Infection significantly influenced the release of only 4 out of the 22 measured cytokines: IL6, IL8, IL18, and MCP-1." (PMID 32664675, 2020). "Early in infection, MCP-1 was markedly increased in parallel with induction of IL-18, a recognized inducer of myloid cell activation with a predilection for NK cells." (PMID 32790668, 2020). "VVΔTK∆N1L infection upregulates the expression of the IL1 family of cytokines from both DCs and macrophages: IL1α, IL1β and IL18." (PMID 32217766, 2020). "ASC specs were found in the plasma of HIV positive patients, and infection with HIV stimulated the NLRP3 inflammasome in monocytes as well as production of caspase-1, IL-1β and IL-18 in brain microglial cells." (PMID 32066471, 2020). "Most of the genes for chemokines/chemokine receptors (CCR2, CCR6, CCR7, CSF2RB, CX3CR1 and CXCR4) and cytokines/cytokines receptors (IL1R2, IL8, IL18, IL20RA and IL22RA2) were down-regulated after infection by vvIBDV at 3 dpi." (PMID 33110122, 2020). "Previous studies showed that IL-22 induces Th1 signature cytokines such as IL-18 and IFN-γ during Toxoplasma gondii experimental infection." (PMID 32517114, 2020).